IFNG (interferon gamma)
Diseases named in the same sentence as IFNG in open-access papers (continued):
Sharing a sentence is not in itself a finding about the gene and the disease.
tumor (continued). "The priming of macrophages with IFNγ leads to the up-regulation of Fcγ receptors, TNFα, and inducible nitric oxide synthase (iNOS); all of which can enhance the killing of tumor cells." (PMID 19148288, 2009). "Adenovirus-mediated intratumoral delivery of the IFNγ gene is a promising approach because it achieves high and sustained local IFNγ expression in the tumor." (PMID 19216804, 2009). "The concentration of IFNγ was highest in the tumor (P < 0.05), followed by the liver and kidney (P < 0.05)." (PMID 19216804, 2009). "We have studied Mage-b-specific CD8 T cells secreting IFNγ, as tumour cell kill is mediated through CD8 function." (PMID 18728665, 2008). "The highest percentage of positive samples (70.6%) to IFNγ was found in the benign lesion group, while in tumor cases the number of positive samples was lower." (PMID 17697357, 2007). "In infiltrating tumor samples, imunoreactions to IFNγ, IFNγ-Rα and IFNγ-Rβ were compared with several tumor parameters (nodal status, TNM system and ER/PR status)." (PMID 17697357, 2007). "Previous work has shown that T cells with a full effector phenotype display the highest levels of IFNγ production and target lysis in vitro, and our tumor-infiltrating full effectors at day 6 possessed the highest cytolytic capacity." (PMID 17786193, 2007). "IFNγ can control tumour growth directly through proapoptotic, antiangiogenic and antiproliferative effects and indirectly, by facilitating induction of antitumour innate and adaptive immune responses." (PMID 17565340, 2007). "Probably directed in part by PGE2, based on reduced production of anti-tumor Th1 cytokines (TNFα, IFNγ and IL-2) and increased production of Th2 cytokines (IL-4, IL-10 and IL-6)." (PMID 19455240, 2007). "In fact, tumours appeared significantly earlier in IFNγ−/− mice treated with CD25-specific mAbs compared to mice receiving the control mAbs." (PMID 17565340, 2007). "It is possible that CD25-specific mAbs deplete important tumour-induced effector cells in IFNγ−/− mice." (PMID 17565340, 2007). "Previous studies have highlighted a critical role for IFNγ in controlling the development of MCA-induced tumours." (PMID 17565340, 2007). "It is difficult to ascertain what numbers of IFNγ-secreting cells or what percentage specific lysis in the immunological experiments would be enough to induce tumor protection in vivo." (PMID 17059610, 2006). "The IL-12-expressing tumours grew more slowly and had much smaller blood vessels than the large, webbed vessels characteristic of the parental tumours, effects that were dependent on interferon gamma (IFN-γ)." (PMID 12778077, 2003). "Studies indicate that CD8+ T cells activated by immunotherapy can downregulate the expression of XCT subunits SLC7A11 and SLC3A2 on tumor cell membranes through the secretion of interferon‐gamma (IFN‐γ), enhancing intracellular lipid peroxidation and leading to tumor cell ferroptosis." (PMID 41560416, 2026). "Furthermore, the protein expression of interferon gamma (IFNγ) was also increased in tumor‐infiltrated CD8+ T cells isolated from LLC1‐bearing mice co‐administered with anti‐PD‐L1 antibodies at ZT16 and AMD3100 at ZT16, but not AMD3100 at ZT4." (PMID 41257391, 2026). "The personalized neoantigen vaccine “NeoVax”, which combines patient-specific neoantigens identified from tumor sampling, has successfully generated immune responses characterized by an increase in interferon-gamma (IFN-γ) producing T-cells and intratumoral T-cell infiltration." (PMID 41504830, 2026). "Notably, blocking Siglec-15 would increase the secretion of interferon gamma (IFN-γ) and interleukin-2 (IL-2) both in vitro and in vivo, significantly inhibiting tumor growth." (PMID 41584035, 2026). "Meanwhile, IFNγ is a potent pro-inflammatory agent and plays a dual role in tumor progression." (PMID 41596451, 2026).
tumor (continued). "For instance, in a mouse model of inflammation-associated tumorigenesis, dysbiosis initially drove an increase in colonic CD8+ IFNγ+ T cells, but these cells later became functionally exhausted within the tumor microenvironment (TME), reducing their efficacy against tumors." (PMID 41486167, 2026). "Furthermore, Ptpn13 knockdown in tumor cells significantly enhanced the expression of the effector cytokines IFNγ and TNFα in CD8+ T cells isolated from CT26-shApc tumors in WT Balbc mice, indicating an increase in CD8+ T cell effector function." (PMID 41486293, 2026). "These IFNγ-mediated anti-tumor activities could potentially contribute to the increased NPC cell death induced by rhCD137L-MSNs, which may be further enhanced by the additive effects of TNF and FasL." (PMID 41328355, 2026). "Regarding immune‐related pathways, the pCR group showed marked enrichment in adaptive immune responses—including T and B cell activation and interferon‐gamma (IFN‐γ) signaling—indicating that a pre‐existing, active immune microenvironment is likely critical for achieving complete tumor regression." (PMID 41541656, 2026). "NK cells, as critical effector cells of the innate immune system, recognize and lyse virus-infected or tumor cells, primarily through the release of cytotoxic granules, and secrete cytokines such as interferon-gamma (IFN-γ) and tumor necrosis factor-alpha (TNF-α) to modulate immune responses." (PMID 41601671, 2026). "Interferon-gamma (IFN-γ) has shown promise in immune cell defense by targeting tumor cells." (PMID 40872475, 2025). "Additionally, the upregulation of interferon-gamma (IFN-γ) response signatures indicates an inflammatory tumor microenvironment (TME), which is more likely to respond to immunotherapy." (PMID 40003691, 2025). "Icaritin can elevate IFNG levels and significantly inhibit tumor growth in combination with ICIs." (PMID 39945555, 2025). "These outcomes, in conjunction with IFNγ-activated JAK/STAT1 signaling, promoted the trans-differentiation of tumor-associated macrophages from the M2 to M1 type, remodeled the suppressive tumor immune microenvironment created by iRFA, and restored therapeutic sensitivity to ICIs." (PMID 39776793, 2025). "Functional analysis of the induced T-cell response in the blood of LS-CoAT-vaccinated animals revealed comparable frequencies of IFNγ/TNFα double-positive Adpgkmut-specific CD8 T cells after complete tumor regression, indicating fully functional cytotoxic effector T cells." (PMID 39741195, 2025). "CD8+ T lymphocytes elicit anti-tumor responses through the production of interferon-gamma (IFN-γ)." (PMID 41438761, 2025). "Moreover, catumaxomab binds to CD3 on T cells, triggering their activation and proliferation, causing tumor-killing molecules such as tumor necrosis factor-alpha (TNF-α), interferon-gamma (IFN-γ), perforin, and granzyme B to be released." (PMID 41275209, 2025). "Regarding bone tumors and skeletal metastases, it was recently demonstrated that combined treatments with denosumab associates with an increased abundance of T cells in the tumor microenvironment (TME) and increased amount of anti-tumor cytokines (such as interferon-gamma)." (PMID 40274631, 2025). "In these cells, DU-14 proved to increase the phosphorylation levels of substrates of both PTPs, such as JAK1 and JAK2, and to amplify IFNγ signaling, thus promoting the recruitment and activation of T lymphocytes and the subsequent recognition and killing of tumor cells." (PMID 41302504, 2025). "To investigate whether IFNγ directly acts on tumor endothelial cells, we analyzed the expression of programmed death ligand 1 (PD-L1) as a readout of IFNγ signaling (Cd274 encoding PD-L1 is an IFNγ-stimulated gene)." (PMID 40460830, 2025).
tumor (continued). "Although CD4+ T cell infiltration was not significantly changed, TNBCvax vaccination enhanced Th1-associated cytokine production (IFNγ and TNFα) which is suggesting a functional shift in CD4+ T cell activity that supports overall immune activation and CD8+ T cell-mediated tumor control." (PMID 40969744, 2025). "Thus we decided to analyze the effects of IFNγ at the concentrations detected in these co-cultures (about 10 ng/mL) treated with TRBs on PD-L1 levels of co-cultured tumor cells." (PMID 39929828, 2025). "To account for additional effector functions of CAR-NK cells besides direct tumor cell killing, we tested TNFα and IFNγ secretion of CD276-directed CAR NK-92 cells after co-incubation with all target cell lines tested before in cell killing experiments (except AR6)." (PMID 40469103, 2025). "Importantly, the serum-derived IFNγ signature for identifying responders to neoadjuvant immunotherapy demonstrated predictive performance comparable to a previously reported tumour-based IFNγ gene signature (AUC = 0.67)." (PMID 41291768, 2025). "The correlation between the intensity of the specific immune response (measured as IFNγ-secreting splenocytes) and the effect on tumor growth, in both therapeutic and prophylactic setups, confirmed a direct effect of the elicited specific T cells against the neoepitopes used in the constructs." (PMID 40160825, 2025). "The stem-derived PDL1- tumor cells can further develop PDL1 + program in the presence of IFNγ." (PMID 40460357, 2025). "Moreover, the significant increase in effector/memory and cytotoxic T-cell populations, including those producing IFNγ and TNFα, also highlights a shift towards a more active immune response capable of targeting and destroying tumor cells." (PMID 40750787, 2025). "CRS results from the robust activation of CAR T cells upon encounter with tumor cells, leading to a surge in pro-inflammatory cytokines, including interleukin 6 (IL-6), interferon gamma (IFNγ), interleukin 1 (IL-1), and tumor necrosis factor alpha (TNF-α), that drive systemic inflammation." (PMID 41323217, 2025). "For inhibitory effects, IFNs (mostly IFNγ) have historically been characterized to be integral for anti-tumor immunity by driving antigen presentation and chemokine secretion that are typically part of the immune-editing process in normal physiological conditions." (PMID 39663510, 2025). "Owing to the sustained from nanoparticle and gel, IFNγ could remain in the residual tumor site for a long time and exert its immune-regulatory effect, while its systemic toxicity and adverse reactions in the normal peripheral tissues were avoided." (PMID 39776793, 2025). "Moreover, it has been shown that the combination of anti-LAG3 and anti-PD1 monoclonal antibodies enhances IFNγ production and T cell cytotoxicity, leading to more effective tumor growth inhibition." (PMID 41019045, 2025). "Therefore, mAb monalizumab increases the cytotoxic activity of NK and T CD8+ cells by blocking the binding of NKG2A/CD94 to HLA-E, which is typically stimulated by anti-tumor activity and Interferon-gamma (IFN-γ)." (PMID 40296914, 2025). "Furthermore, by analyzing gene expression in HCC tumor tissues from patients enrolled in the STORM trial, we observed that IFNγ production was associated with a better response to sorafenib." (PMID 40645933, 2025). "Analysis of tumor biopsies has shown that acquired resistance may stem from defects in interferon-gamma (IFN-γ) signaling pathways." (PMID 40963596, 2025). "However, studies have shown that IFNγ can also upregulate PD-L1 expression on tumor cells, thereby facilitating tumor immune evasion and promoting tumor progression 39-42." (PMID 40521193, 2025). "When T cells recognize tumor antigens, they upregulate PD-1 and secrete interferon-gamma (IFN-γ)." (PMID 40006624, 2025).
tumor (continued). "This could look like the following: Initially, IFNγ-secreting CAR-Ms would recognize and phagocyte the tumour, with continuous IFNγ secretion inducing the recruitment of chemokine-expressing CAR-NK cells." (PMID 40650066, 2025). "In tumor, IFNγ levels and Granzyme B expression were also increased, a fact that might indicate a shift to a pro-inflammatory microenvironment derived from the inactivation of Tregs by ILs." (PMID 39075226, 2025). "Thus, NK cells lose their capacity to produce IFNγ over time and as such, CD8+ T cells remain the main source of IFNγ, even in IFNγRKO tumours." (PMID 39746898, 2025). "IFNα and IFNγ are essential for antiviral and antitumor immunity: IFNγ activates macrophages and boosts antigen presentation, while IFNα enhances immune detection of tumor cells." (PMID 40444484, 2025). "The cytokines, such as IFNα, IFNγ, and TNFα, were shown to increase the splicing activities of PD-L1 leading to the secretion of sPD-L1 directly by tumor cells; thus, elevated levels of sPD-L1 were found to correlate with disease progression in a study on melanoma patients." (PMID 40283180, 2025). "Moreover, a single dose of CBL0137 significantly increased IFNγ levels in the serum of 4T1.2 tumor-bearing mice." (PMID 39706891, 2025). "Because of the action of this drug on T cells, it could lead to the production of interferon-gamma, a cytokine that can induce M1 polarization of macrophages, supporting a more robust anti-tumor response." (PMID 39827422, 2025). "As we also observe this immune landscape remodelling in humans, it highlights the relevance of our findings and provides potential new therapeutic avenues, which could be important beyond IFNγ-insensitive tumours." (PMID 39746898, 2025). "Third, we explicitly couple immune phenotypes with tumour evolutionary trajectories, revealing that C4 tumours represent immune‐inflamed “hot” states (PD‐L1/IFNγ upregulated, MES‐like), whereas C2 tumours represent immune‐desert “cold” states (low MHC, CD160 upregulated, PN‐like proliferative)." (PMID 41292185, 2025). "Traditional studies in solid tumors have shown that CD4 TH cells sustain anti‐tumor activity by directing other leukocytes, enhancing tumor‐antigen presentation, and directly inhibiting tumor proliferation via interferon gamma (IFN‐γ) and tumor necrosis factor alpha (TNF‐α)." (PMID 40571973, 2025). "Importantly, increased levels of tumor infiltrating CD8+ T cell and tumor-reactive IFNγ+ CD8+ T cells by the combination treatment of anti-PD-1 and siHmgcr-CNPs were reversed upon Lip-1 treatment." (PMID 41339438, 2025). "In IFNγRKO tumours, higher IFNγ levels may increase adhesion of lymphocytes and monocytes to intra-tumoural endothelium, which we observe as a quantifiable increase in these cell–cell interactions." (PMID 39746898, 2025). "In contrast, while Lac or PD-1 antibody treatment did not significantly alter infiltration of CD4+ and CD8+ T cells into tumors (Fig. EV5D,E), these treatments activated tumor-infiltrating T cells as revealed by enhanced expression of IFNγ and perforin (J and EV5F)." (PMID 39979425, 2025). "Since CD8+ T cells are a major source of IFNγ in the tumor microenvironment, we then tested whether tumor-specific CD8+ T cells could augment sorafenib sensitivity." (PMID 40645933, 2025). "In the current approach, CCL2 is intended to attract M2-like macrophages located in the tumor periphery toward the cryogel, where they will come into contact with interleukin-12 (IL-12) and interferon gamma (IFN-γ) and be polarized toward M1-like characteristics." (PMID 40883548, 2025). "Because most tumors are MHC class II negative, we assume that IFNγ produced by vaccine-specific CD4+ T cells can upregulate HLA-DR expression in tumor cells, making them susceptible to lysis." (PMID 40543509, 2025).
tumor (continued). "By utilizing a pathological Gradient Boosting Machine (GBM) model, this study aims to explore the correlation between PS and IFNG expression, and to validate their consistency in predicting prognosis, providing a novel tool for assessing tumor immunity and aiding in personalized treatment planning." (PMID 41368643, 2025). "Additionally, cytokine-based therapies, including immune-stimulating molecules such as IL-2, GM-CSF, and interferon-gamma, are being explored to enhance immune activation and counteract the immunosuppressive tumor microenvironment in EwS." (PMID 40242222, 2025). "Recently, it was reported that a 1,2,5-thiadiazolidine derivative, ABBV-CLS-484 (AC484), able to potently inhibit both TCPTP and PTP1B at very low nanomolar concentrations, amplifies responsiveness of tumor cells to IFNγ, promotes T cell activation and impairs tumor growth in mice." (PMID 41302504, 2025). "Notably, the response of non‐tumor tissue was significantly stronger when comparing final concentrations of IFNγ and IL‐2 after treatment." (PMID 40952312, 2025). "Antibody-drug conjugates (ADCs) NSCLC-derived tumor cells produce IL-18, which is a key factor in driving type 1 (IFNγ-producing) responses of CD8C T-cells with high levels of IL-18 receptor (IL-18R), which are balanced by dysfunctional T-cells with low levels of IL-18R in ADC NSCLC." (PMID 41179937, 2025). "However, by upregulating PD-L1 and CXCL10, IFNγ directly enhances and reduces the immunogenicity of tumor cells." (PMID 40264756, 2025). "Although Tnfrsf14 knockdown in ID8 cells did not alter the frequency of CD8+ T cells or CD8+ TEM in the ascites, the robust elevation in the number of cytotoxic T lymphocytes (CTLs, IFNγ‐producing CD8+ T cells) in Tnfrsf14KD‐ID8 tumor‐bearing mice indicates enhanced antitumor immunity." (PMID 40105652, 2025). "Loss of CCR2 also decreased the frequency of OVA-specific T cells in IFNγRKO-tumour bearing mice compared with WT mice, which indicates that monocyte recruitment is necessary for the recruitment and/or retention of antigen/tumour-specific CD8+ T cells in IFNγ-insensitive tumours." (PMID 39746898, 2025). "Thus, apCAFs can be formed from PSCs through treatment with IFNγ or exposure to activated T-cells but diffusible factors from tumor cells suppress apCAF formation." (PMID 40215177, 2025). "Notably, this treatment increased the proportion of M1 macrophages expressing IL12 and IFNγ, leading to a more immunostimulatory tumor microenvironment." (PMID 40330466, 2025). "To do so, we admixed WT and IFNγRKO B16-OVA tumour cells in vitro and added IFNγ to the culture." (PMID 39746898, 2025). "Furthermore, functional inhibition of CXCR4 in tumor cells was discovered to effectively inhibit the immunosuppressive role of MICs by restoring T cell proliferation and IFNγ expression, and partly by blocking TAM polarization." (PMID 41023740, 2025). "Blocking EGFR might reshape the tumor microenvironment, enhancing NK cell function through cytokine release (e.g., IL-12, IL-15) and interferon-gamma." (PMID 40869384, 2025). "In addition, one of its ligands, PD-L1, can be expressed on a wide range of cell types, including T cells, epithelial cells, endothelial cells, and tumor cells after exposure to the cytokine interferon-gamma (IFN-γ) produced by activated T cells." (PMID 41200193, 2025). "IFNγ signatures pre- and post-ICB treatment are associated with clinical response to therapy, and it was often assumed that the main mode of action of IFNγ is to directly inhibit and/or kill tumour cells." (PMID 39746898, 2025). "To characterise how CD8+ T cells and IFNγ led to the selection of IFNγRKO tumour cells in our admix setup, we first analysed whether IFNγ had a direct cytostatic effect on WT tumours." (PMID 39746898, 2025).